KIT (KIT proto-oncogene, receptor tyrosine kinase)
Diseases named in the same sentence as KIT in open-access papers (continued):
Sharing a sentence is not in itself a finding about the gene and the disease.
gastrointestinal stromal tumor (continued). "Numerous studies have linked gastrointestinal stromal tumors to gene mutations in tyrosine kinase receptor (KIT) and platelet-derived growth factor receptor-alpha (PDGFRA)." (PMID 34991597, 2022). "Since KIT is activated by overexpression or mutation and plays an important role in the development of some cancers, such as gastrointestinal stromal tumors and mast cell disease, molecular therapies targeting KIT mutations are being developed." (PMID 35563085, 2022). "The canonical mutations in gastrointestinal stromal tumors (GISTs) are typically activating mutations in KIT and platelet-derived growth factor receptor alpha (PDGFRA)." (PMID 35681640, 2022). "Currently, imatinib is only approved for gastrointestinal stromal tumours with oncogenic KIT mutations." (PMID 35849877, 2022). "Gastro-intestinal stromal tumors and acute myeloid leukemia induced by activating stem cell factor receptor tyrosine kinase (KIT) mutations are highly malignant." (PMID 36396684, 2022). "In gastrointestinal stromal tumors, the location of KIT mutations is associated with tumor biological behavior, and exon 11 and 13 mutations provide evidence regarding the tumors’ malignant biological status." (PMID 35488288, 2022). "Thought to differentiate into Cajal cells, the majority of gastrointestinal stromal tumors (GISTs) harbor mutually exclusive KIT or PDGFRA mutations, which drive tumorigenesis and dictate responses to imatinib." (PMID 35406559, 2022). "KIT mutations in primary melanoma are composed of missense substitutions on different exon distribution in comparison to KIT-mutated gastrointestinal stromal tumor." (PMID 34571863, 2021). "A noteworthy exception is represented by gastrointestinal stromal tumors, wherein activating mutations in either KIT or PDGFRα genes drives tumor proliferation." (PMID 34944915, 2021). "The mutation of KIT is an important mechanism in gastrointestinal stromal tumors (GIST), but its role in GC is still unclear." (PMID 33794777, 2021). "The presence of point mutations in the KIT gene has also been observed in gastrointestinal stromal tumours (GIST)." (PMID 34203771, 2021). "In fact, the first descriptions of the role of c-KIT as a cause of human tumors were reported in hematologic and gastrointestinal stromal tumors." (PMID 34439864, 2021). "Activating KIT mutations are present in 75–85% of gastrointestinal stromal tumors (GISTs), representing the main oncogenic driver." (PMID 33995103, 2021). "Some of the molecular events found in sarcomas are druggable, such as tyrosine-protein kinase (KIT) mutations in gastrointestinal stromal tumors (GISTs) and in a minority of other mesenchymal tumors." (PMID 33478080, 2021). "Gastrointestinal stromal tumors (GISTs) nearly always carry activating mutations of c-KIT, a proto-oncogene or platelet-derived growth factor receptor-α gene, giving ground to treatment with TKIs." (PMID 33478080, 2021). "Management of gastrointestinal stromal tumors (GISTs) has been revolutionized by the identification of activating mutations in KIT and PDGFRA and clinical application of RTK inhibitors in advanced disease." (PMID 33320833, 2021). "For gastrointestinal stromal tumor, the prevalence of the KIT mutation was similar between the two groups, but our cohort had a significantly higher prevalence of CDKN2A and NF1." (PMID 32373528, 2020). "The KIT gene is associated with autosomal dominant piebaldism, gastrointestinal stromal tumors (GISTs), and familial mastocytosis." (PMID 32570972, 2020). "Despite the effectiveness of imatinib mesylate (IM), most gastrointestinal stromal tumours (GISTs) develop IM resistance, mainly due to the additional kinase-domain mutations accompanied by concomitant reactivation of KIT tyrosine kinase." (PMID 31857719, 2020). "KIT mutations are the predominant driver mutations in gastrointestinal stromal tumors (GISTs), and targeted therapy against KIT has improved treatment outcome dramatically." (PMID 32082541, 2020).
gastrointestinal stromal tumor (continued). "Most gastrointestinal stromal tumors (GISTs) arise due to gain-of-function mutations of KIT and PDGFRA, encoding the receptor tyrosine kinase (RTK)." (PMID 33066449, 2020). "Most gastrointestinal stromal tumours (GIST) are driven by activating oncogenic mutations of KIT/PDGFRA, which provide a compelling therapeutic target." (PMID 31776458, 2020). "Although the majority of gastrointestinal stromal tumors (GISTs) possess KIT mutations that induce constitutive signal transduction, the clinical outcomes are variable." (PMID 32901065, 2020). "Secondly, 1 inhibited in a good manner PDGFRs (especially PDGFR-β) and the mutations that occur in the exon 11 of the KIT gene, which encodes the juxta-membrane domain (V559D and L576P) involved, for example, in gastrointestinal stromal tumors." (PMID 33218150, 2020). "KIT mutations are common in gastrointestinal stromal tumors (GIST), where they are also predictive of response to the tyrosine kinase inhibitor, imatinib." (PMID 32485873, 2020). "The majority of gastrointestinal stromal tumors (GISTs) are driven by a constitutively activating mutation in the KIT or PDGFRA (platelet-derived growth factor receptor alpha) receptor tyrosine kinase." (PMID 32198455, 2020). "Gastrointestinal stromal tumors (GISTs), the most common mesenchymal tumors of the gastrointestinal tract, are characterized by activating mutations in KIT or PDGFRA genes." (PMID 33212994, 2020). "Up to 85% of gastrointestinal stromal tumors (GIST) harbor mutually exclusive mutations in the KIT or the PDGFRA gene." (PMID 31124195, 2019). "The excessive activation of c- KIT or specific mutations in c-KIT have been implicated in a number of human cancers, such as gastrointestinal stromal tumors (GISTs), pancreatic cancer, melanoma and haematological neoplastic diseases." (PMID 31590335, 2019). "KIT mutations in exon 11 and 14 are known to occur in thymic cancer and cutaneous melanoma, and gastrointestinal stromal tumors, respectively." (PMID 30847022, 2019). "Imatinib shows limited efficacy in patients with gastrointestinal stromal tumors (GISTs) carrying secondary KIT mutations." (PMID 31673329, 2019). "Activating mutations of the receptor tyrosine kinase KIT are early events in the development of most gastrointestinal stromal tumors (GISTs)." (PMID 30867899, 2019). "Gastrointestinal stromal tumors (GISTs) are characterized by the presence of activating mutations in KIT or PDGFRα genes." (PMID 30472630, 2018). "Gastrointestinal stromal tumors (GISTs) are characterized by oncogenic KIT mutations that cluster in two exon 11 hotspots." (PMID 29568401, 2018). "Gastrointestinal stromal tumors (GISTs) are the most common mesenchymal tumors of the gastrointestinal tract and are characterized by the gain-of-function mutations of KIT and platelet-derived growth factor alpha (PDGFRA) gene." (PMID 30313116, 2018). "Gain-of-function mutations and overexpression of KIT are characteristic features of gastrointestinal stromal tumor (GIST)." (PMID 29661252, 2018). "Mutations of KIT are associated with several human malignancies, most notably gastrointestinal stromal tumors, acute myeloid leukemia, mastocytosis and melanoma." (PMID 30470245, 2018). "Mutations in PDGFR family genes, particularly PDGFRα and c-KIT, are most frequently found in gastrointestinal stromal tumors (GISTs)." (PMID 30404198, 2018). "Gastrointestinal stromal tumors (GISTs) are caused by the constitutive activation of KIT or platelet-derived growth factor receptor alpha (PDGFRA) mutations." (PMID 28487491, 2017). "KIT kinase V559D mutation is the most prevalent primary gain-of-function mutation in Gastrointestinal Stromal Tumors (GISTs)." (PMID 29340041, 2017). "Currently, molecular therapies are available mainly for the treatment of gastrointestinal stromal tumor, a soft-tissue malignancy characterized by an activating mutation of the tyrosine kinase KIT." (PMID 28955656, 2017).
gastrointestinal stromal tumor (continued). "Most gastrointestinal stromal tumors (GISTs) harbor mutually exclusive gain of function mutations in the receptor tyrosine kinase (RTK) KIT (70–80%) or in the related receptor PDGFRA (~10%)." (PMID 28768491, 2017). "It was reported that the allelic variants of KIT would lead to various diseases including piebaldism, mast cell leukemia, gastrointestinal stromal tumor and so on." (PMID 29050270, 2017). "Nearly contemporaneously, imatinib was shown to be an effective KIT inhibitor and to be useful for the treatment of KIT-mutated gastrointestinal stromal tumor, as well." (PMID 27784327, 2016). "It has been documented that the c‐KIT inhibitor, imatinib, caused macrocytosis in patients treated for gastrointestinal stromal tumors (GIST)." (PMID 27758076, 2016). "This tyrosine-inhibitory compound has been successful in targeting KIT mutations and related genetic aberrations in gastrointestinal stromal tumor (GIST), chronic myeloid leukemia and other c-kit expressing tumors." (PMID 27509178, 2016). "This pathway is already highly relevant in some sarcomas, since mutated c-KIT is a known driver oncogene in gastrointestinal stromal tumors (GIST)." (PMID 27409346, 2016). "It is commonly used in the treatment of gastrointestinal stromal tumors (GIST) in which there are mutations of the KIT gene." (PMID 27737004, 2016). "Imatinib is the first-line drug for gastrointestinal stromal tumors (GISTs), as mutated KIT is closely associated with the occurrence of GIST." (PMID 26587973, 2016). "Despite known targeted therapeutic options in solid tumors (KIT or PDGFRA mutations in gastrointestinal stromal tumors), STS still lacks therapeutically relevant genetic alterations." (PMID 27016421, 2016). "In this study, these two theories were evaluated in gastrointestinal stromal tumours (GISTs) where most patients develop secondary resistance mutations in the KIT gene during therapy with tyrosine kinase inhibitors." (PMID 25886408, 2015). "Many types of KIT mutations have been observed in gastrointestinal stromal tumors (GISTs), but their prognostic and predictive significance are still unclear." (PMID 26349547, 2015). "Gastrointestinal stromal tumors are sarcomas of the digestive tract characterized by mutations mainly located in the c-KIT or in the platelet-derived growth factor receptor (PDGFR)-alpha genes." (PMID 25885906, 2015). "The activating mutation (D820E) in exon 17 of KIT tyrosine kinase in a patient showing rapid progression within 28 days has been previously reported in imatinib-resistant gastrointestinal stromal tumors." (PMID 26462025, 2015). "Approximately 10–15 % of gastrointestinal stromal tumors (GISTs) lack gain of function mutations in the KIT and platelet-derived growth factor receptor alpha (PDGFRA) genes." (PMID 26555092, 2015). "It has been successfully used for the treatment of CML, as well as gastrointestinal stromal tumors, which are typically driven by gain-of-function mutations in the KIT tyrosine kinase receptor." (PMID 25274034, 2014). "Gastrointestinal stromal tumors (GISTs) are mesenchymal tumors of the gastrointestinal tract, which are characterized in the majority of cases by activating mutations in KIT and platelet-derived growth factor receptor alpha (PDGFRA)." (PMID 24802226, 2014). "A KIT gain of function mutation is present in 70% of gastrointestinal stromal tumors (GISTs) and the wild-type (WT) allele is deleted in 5 to 15% of these cases." (PMID 25373456, 2014). "Acquired resistance to tyrosine kinase inhibitors (TKIs) in gastrointestinal stromal tumours (GISTs) is most commonly caused by secondary KIT or PDGFRA mutations." (PMID 25132955, 2014). "KIT autophosphorylation caused by mutation of KIT is considered to be a critical mechanism for the oncogenesis of gastrointestinal stromal tumors (GISTs)." (PMID 23420128, 2013).
gastrointestinal stromal tumor (continued). "Gastrointestinal stromal tumors are rare soft tissue sarcomas that typically develop from mesenchymal cells with acquired gain-in-function mutations in KIT or PDGFRA oncogenes." (PMID 24159917, 2013). "Gastrointestinal stromal tumors (GISTs) are the most frequent mesenchymal neoplasms of the gastrointestinal tract and are characterized by activating mutations of KIT or platelet-derived growth factor receptor alpha (PDGFRA)." (PMID 22662219, 2012). "Proto-oncogene c-KIT encoded tyrosine kinase appears to have an important role in carcinogenesis of various tumors, including gastrointestinal stromal tumors (GIST), melanomas, seminomas, glioblastomas, breast cancer and acute myeloid leukemias (AML)." (PMID 22839358, 2012). "A subset of KIT/PDGFRA wild-type gastrointestinal stromal tumors (WT GIST) have been associated with alteration of the succinate dehydrogenase (SDH) complex II function." (PMID 22974104, 2012). "KIT has been implicated in the pathogenesis of several cancers including acute myeloid leukemia and gastrointestinal stromal tumors (GIST)." (PMID 22385436, 2012). "Activating c-KIT mutations have been implicated in a variety of cancers starting with GIST (Gastrointestinal stromal tumors) and CML (Chronic Myelogenous Leukemia)." (PMID 21479172, 2011). "A variety of mutations in the gene encoding the proto-oncogene KIT were found in different types of human cancer, in gastrointestinal stromal tumors (GISTs), acute myeloid leukemia (AML), mast cell leukemia (MCL) and human germ cell tumors, among others." (PMID 21698178, 2011). "This study was able to ascertain c-KIT and PDGFRA mutational status of seventeen of eighteen KIT positive canine gastrointestinal stromal tumors, representing a good amplification success rate of 94% from FFPE tissues." (PMID 20950418, 2010). "For example, similar mutations in KIT, a tyrosine kinase growth factor receptor, have been identified in both human gastrointestinal stromal tumours (GIST) and dog mast-cell cancers." (PMID 19327144, 2009). "Pathologic activation of KIT through gain-of-function mutations leads to neoplasia of KIT-dependent and KIT-positive cell types in different systems: Cajal cells - gastrointestinal stromal tumors (GISTs), myeloid cells - myeloid leukemia." (PMID 19811659, 2009). "Gastrointestinal stromal tumours (GISTs) represent a heterogeneous group of tumours of mesenchymal origin characterized by gain-of-function mutations in KIT or PDGFRA of the type III receptor tyrosine kinase family." (PMID 19943934, 2009). "Imatinib blocks KIT signalling, causing the proliferative arrest of gastrointestinal stromal tumours (GISTs), and the inactivation of ERK 1/2." (PMID 20003259, 2009). "The finding of gain-of-function mutation of KIT has revolutionized the treatment of advanced gastrointestinal stromal tumor (GIST)." (PMID 19159438, 2009). "Well-established examples include KIT mutations in gastrointestinal stromal tumors (GISTs) that predict response to imatinib or nilotinib, and non-small cell lung cancers with EGFR mutations that are sensitive to erlotinib." (PMID 19924296, 2009). "Gastrointestinal stromal tumours that harbour different KIT or PDGFRA mutations have different molecular signatures at the level of gene expression, which further contributes to the complexity of GIST biology and variable response to treatment." (PMID 18253129, 2008). "Palliative imatinib treatment has dramatically improved survival in patients with malignant gastrointestinal stromal tumours, particularly in patients with tumours harbouring activating KIT mutations." (PMID 17533389, 2007). "In human patients, mutations in the c-KIT proto-oncogene have been implicated in the pathogenesis of multiple neoplastic diseases, including mastocytosis, germ cell tumors, and gastrointestinal stromal tumors (GISTs)." (PMID 16579858, 2006).
gastrointestinal stromal tumor (continued). "Mutations in the c-KIT proto-oncogene have been implicated in the progression of several neoplastic diseases, including gastrointestinal stromal tumors and mastocytosis in humans, and cutaneous mast cell tumors (MCTs) in canines." (PMID 16579858, 2006). "KIT is the main oncogene in gastrointestinal stromal tumours (GISTs), and gain-of-function KIT mutations are present in 70% of these tumours." (PMID 16570044, 2006). "Somatic mutations of the KIT gene have been reported in mast cell diseases and gastrointestinal stromal tumours." (PMID 15150569, 2004). "Gastrointestinal stromal tumors (GISTs) are the most common mesenchymal neoplasms of the gastrointestinal tract and originate from the interstitial cells of Cajal, with most driven by activating mutations in KIT or PDGFRA." (PMID 41517566, 2026). "Mutations of EGFR have been identified as a cause of non-small-cell lung cancer (NSCLC), overexpression of HER2 is associated with breast cancer, and mutations of KIT (V-kit Hardy-Zuckerman 4 feline sarcoma viral oncogene homolog) are implicated in gastrointestinal stromal tumours." (PMID 40563591, 2025). "Indeed, most cases of mast cell leukaemia in adult humans, as well as patients with gastrointestinal stromal tumours (GISTs), harbour KIT mutations." (PMID 40770227, 2025). "In addition, different mutations in the same gene are not always effectively inhibited by the same targeted therapy, as has been observed in gastrointestinal stromal tumors with KIT mutations and in lung cancer with EGFR mutations." (PMID 39941744, 2025). "Most gastrointestinal stromal tumors (GISTs) harbor c-KIT or PDGFRA mutations." (PMID 38992597, 2024). "With the notable exception of gastrointestinal stromal tumor which is predominantly driven by gain-of-function mutations in the genes encoding KIT or PDGFRA receptor tyrosine kinases, it is challenging to design a ctDNA assay in sarcoma dependent on recurrent SNVs." (PMID 39737274, 2024). "Mutations in the c-KIT or PDGFRα genes primarily drive gastrointestinal stromal tumors (GISTs)." (PMID 39917203, 2024). "Additionally, mutations in the KIT gene, associated with leukemia and gastrointestinal stromal tumors, have been linked to the pathogenesis of malignant melanoma." (PMID 39036271, 2024). "One group of sarcomas (20%) is characterized by specific genetic changes and typically simple karyotypes, such as specific chromosomal translocations (e.g., FUS::DDIT3 in myxoid liposarcoma [MLPS]) and oncogenic mutations (e.g., KIT mutation in gastrointestinal stromal tumor [GIST])." (PMID 36983010, 2023). "KIT mutation is found in 80% of gastrointestinal stromal tumors." (PMID 38313431, 2023). "Rare gastrointestinal stromal tumors (GISTs) are caused by mutations in the KIT and PDGFRA genes." (PMID 38004483, 2023). "Moreover, we observed the same results in gastrointestinal stromal tumor (GIST) cell lines where a gain of function mutations on KIT or PDGFRA were the oncogenic drivers." (PMID 36834926, 2023). "The most common mutations in gastrointestinal stromal tumors (GISTs) are KIT or PDGFRA mutations." (PMID 36612101, 2022). "TKIs can effectively treat KIT or PDGFRA mutated gastrointestinal stromal tumors (GISTs)." (PMID 35685436, 2022). "Succinate dehydrogenase deficient (SDH-deficient) gastrointestinal stromal tumors (GISTs), as defined by the expression loss of the subunit B of the succinate dehydrogenase complex, account for approximately 20% to 40% of all KIT/PDGFRA wild-type (WT) GISTs and 5% of all GISTs." (PMID 33806389, 2021). "Most gastrointestinal stromal tumors (GISTs) are driven by activating oncogenic mutations of receptor tyrosine kinase (RTK) KIT/PDGFRA, which provide a compelling therapeutic target, as evidenced by the clinical successes of KIT/PDGFRA-inhibition by small molecule therapeutics." (PMID 34025442, 2021).